TNF (tumor necrosis factor)
Diseases named in the same sentence as TNF in open-access papers (continued):
Sharing a sentence is not in itself a finding about the gene and the disease.
leukemia (continued). "Res and ω-3 PUFA reduced IL-1β, IL-6, TNF-α, CXCL10/IP-10, CCL13/MCP-4 and CCL20/MIP-3α in LPS/IFN-γ activated human leukaemia THP-1 cells, which is indicative of a dampening effect on M1 macrophages." (PMID 35884829, 2022). "Analyzing gene expression patterns of apoptosis and leukemia-related pathway members following VEN incubation, we revealed that TNF signaling, previously unrelated to VEN response, regulates apoptosis induction and thus possible VEN resistance in SEM cells." (PMID 35778418, 2022). "When analyzing the target cells for the expression of the membrane-bound ligand of TIM-3, CEACAM1, we observed that many leukemia and lymphoma cell lines upregulate CEACAM1 when exposed to Th1 cytokines IFN-γ and TNF-α." (PMID 35464394, 2022). "TNF-α also inhibited the proliferation of mouse myeloid leukemic WEHI-3B JCS cells and human promyelocytic HL-60 leukemia cells, inducing their differentiation into monocytes and macrophages." (PMID 35160591, 2022). "Treatment of human leukemia THP-1 cells with BF-induced inflammatory cytokine interleukin-1 beta (IL-1β) and tumor necrosis factor-α (TNF-α)." (PMID 36235123, 2022). "Luteolin was reported to show degranulation inhibitory activities in antigen-stimulated rat basophil leukemia RBL-2H3 cells (IC50 5.8 μM), and suppressed Substance P (SP) or IgE/anti-IgE–stimulated β-Hex, histamine and TNF-α release from LAD2 mast cells." (PMID 36496664, 2022). "Based on this, the cell viability and immune factors of mouse mononuclear macrophage leukemia cells (RAW264.7) were used for evaluating the immune activity on CMPP, such as nitric oxide (NO), tumor necrosis factor α (TNF-α) and interleukin 6 (IL-6)." (PMID 35681381, 2022). "In human leukemia and myeloma cells, NOSC inhibited NF-kB through NF-kB kinase turning the neoplasic cells sensitive to tumor necrosis factor and chemotherapy." (PMID 34069423, 2021). "While TNF‐α gene therapy had limited efficacy, IFN‐γ gene therapy showed a substantial initial reduction in leukemia development, followed by leukemia progression in most animals (Fig EV2A)." (PMID 34459560, 2021). "There is a very similar regulatory cascade in leukemia cells, where transcription factor NFkB recruits the MLL1 histone methyltransferase complex to activate NFkB target genes after TNF treatment." (PMID 32094334, 2020). "Kurosawa and colleagues found that treating human leukemia THP-1 cells with bufalin induced inflammatory cytokines interleukin-1β (IL-1β) and tumor necrosis factor-α (TNF-α)." (PMID 30200235, 2018). "Crude organic extracts of turmeric-inhibited lipopolysaccharide (LPS)-induced production of tumor necrosis factor (TNF)-α (IC50 = 15.2 μg/mL) and prostaglandin E2 (PGE2; IC50 = 0.92μg/mL) in human leukemia (HL-60) cells." (PMID 30200410, 2018). "Murine macrophages (RAW264.7 cells), human monocytic/leukemia cells (THP-1), PBLs and HUVECs were incubated with RES and activated with inflammatory stimuli such as LPS or TNF-α." (PMID 28610607, 2017). "The TNF-alpha, SIN3 and NCOR1 related complex were reported to have close relationship with leukemia." (PMID 26822725, 2016). "Tumor necrosis factor (TNF)-related apoptosis-inducing ligand-TNFSF10 (TRAIL), a death receptor ligand, is down-regulated in BCR-ABL1-positive leukemia." (PMID 27233483, 2016). "In U937 leukemia cells, RA (60 μM) enhanced TNF-α induced apoptosis and decreased TNF-α induced-NF-κB activation and ROS production." (PMID 27869665, 2016). "The production of IL-2, TNF-a and IFN-r secreted by PD1hiTIM3+ cells were reduced in leukemia patients." (PMID 27447564, 2016). "For example, TNF-α is expressed at a high level by AML blasts and mainly enhances production of the cytokines IL-1β and GM-CSF in terms of leukemia growth control; other studies demonstrated that TNF-α can induce apoptosis in leukemic cells." (PMID 26516703, 2015).
leukemia (continued). "Using an IL-32θ stable expression system in leukemia cell lines, we found that IL-32θ attenuated phorbol 12-myristate 13-acetate (PMA)-induced TNF-α production." (PMID 26516703, 2015). "We also analyzed the mechanism of TNF-α downregulation via suppression of p38 MAPK and NF-κB activities in phorbol 12-myristate 13-acetate (PMA)-activated leukemia cell lines." (PMID 26516703, 2015). "For example, the combination of GM-CSF, IL-4, and TNFα induced the expression of MHC II, CD40, CD86, CD1a, CD1b, and CD1c by neutrophil-committed precursors isolated from leukemia patients receiving G-CSF treatments." (PMID 24278484, 2013). "Zinc deficiency increases the expression of cytokine-related genes (TNF; IL1B; IL8) in leukemia cell-lines." (PMID 22191060, 2011). "Such a phenomenon has been reported for leukaemias, where CXCL13-expressing malignant B cells showed an increased resistance against TNF-α-mediated apoptosis." (PMID 18781150, 2008). "Using different in vitro models of CAR123 co-culture with BPDCN and AML cell lines, we show that both TKIs reduce CAR123 activation phenotype (CD69 and CD25), tumor necrosis factor α (TNF-α) and interferon-γ (IFN-γ) secretion; degranulation (CD107a); and killing of leukemia cells." (PMID 41477551, 2025). "CD70, a member of the tumor necrosis factor (TNF) family, is transiently expressed on activated T and B cells under normal physiological conditions but is aberrantly overexpressed in various hematological malignancies, notably leukemias." (PMID 40227793, 2025). "As-A is shown herein to bind to HDC and exhibit a similar effect on leukemia development resulting in inhibition of several anti-inflammatory genes including TNF, IL1A/B, TNFA1P3, and CXCR2, but not IL6." (PMID 39769192, 2024). "By directly interacting with leukemia stem cells (LSCs), human ILC1s can eliminate LSCs via production of IFNγ and block LSC differentiation into M2 macrophage-like, leukemia-supporting cells through TNF." (PMID 36711868, 2023). "Previously, proteasome inhibition was shown to induce necroptosis in MEFs and human leukemia cells without the need of caspase inhibition and TNF stimulation, but through the accumulation of K48-poly-ubiquitinated RIPK3." (PMID 37495567, 2023). "It has been demonstrated that MSA-2 can activate mouse and human STING genes, induce the phosphorylation of TBK1 and IRF-3 and activate the STING signal pathway in the human leukemia monocytic cell line (THP-1 cells) and induce the expression of IFN-β, IL-1β and TNF-α via the action of TBK1." (PMID 38005816, 2023). "We also observed the upregulation of the TNF, TNF receptor member 1 (TNF-R1), and TNF-R member 6 (FAS) genes, and enhanced expression of BAX, an important effector of the extrinsic apoptotic pathway in leukemia cells." (PMID 36294912, 2022). "When B-ALL cells were cultured in unconditioned medium or SCM, the total number of leukemia cells increased by 6 to 10-fold over 3 days; whereas, all of the B-ALL cell lines cultured in ACM or recombinant TNF-α (a component of ACM) exhibited a 2 to 4-fold increase in density over the same period." (PMID 35241678, 2022). "The status (such as the proliferation and differentiation, self-renewal, LSC harbor, hematopoietic support) of MSCs is different in different types of leukemia, along with the change of HSC-supported CXCL12, inflammatory TNFα, NF-κB signaling, proliferated WNT-β-catenin signaling, and so on." (PMID 35756991, 2022). "Compared with MHC matching, haplomatching of leukemia cells’ MHCs with recipient mouse T cells prolongs leukemic mouse survival, mainly via reduced T cell apoptosis and enhanced secretion of T cell cytokines including IFN-γ and TNF-α." (PMID 34990406, 2022). "TNF-α secretion by Shiga-CAR T cells was specific to recognising Gb3 since it was absent upon incubation with Gb3− Namalwa leukaemia cells." (PMID 36097202, 2022).
leukemia (continued). "The dysregulation of the expression of pro- and anti-inflammatory mediators, such as tumor necrosis factor-α (TNF-α) and interleukins, may significantly promote leukemia cell growth and survival in AML." (PMID 35806401, 2022). "Our results showed that extracellular treatment with SEM-Mb, but not Mb, activated the TNF-α-mediated death pathway in leukemia cells." (PMID 36145287, 2022). "For example, TIM-3+PD-1+CD8+ T cells in mice with advanced AML exhibited severe exhausted phenotype as defined by failure to produce IL-2, tumor necrosis factor and interferon-γ, and combined targeting of TIM-3 and PD-1 pathways was more effective in controlling the leukemia burden." (PMID 35494006, 2022). "The cellular populations and several molecular mechanisms involved in leukemic progression also often overlap, with mesenchymal lineage cells and endothelial cells being common targets of leukemia‐derived inflammatory signals (CCL3, TNF, CXCL12) identified across multiple leukemic subtypes." (PMID 34693187, 2021). "Studies in mouse models with B-ALL have shown that TNF-α is secreted by B-ALL cells, and this leads to increased invasiveness and significant prolongation of surviving leukemia cells, which is an important mediator of leukemia-induced NK cell dysfunction." (PMID 34867958, 2021). "We are also initiating a clinical trial of CB-based HSCT in adult patients with leukemia who will receive two CB grafts: one prepared in the TNFα-supplemented DL-4 culture system and one that has not been manipulated." (PMID 34117371, 2021). "In addition, GLA significantly reduced the release of histamine and β-hexosaminidase, calcium influx, cytokine (IL-4, TNF-α, IL-1β, IL-13, and IL-8) production in the RBL-2H3 (rat basophilic leukemia cells), and RPMCs (peritoneal mast cells) in vitro." (PMID 34007295, 2021). "However, the co-integration of 2B4 and CD3ζ significantly enhanced all aspects of the NK cell activation response to antigen-expressing leukemia or neuroblastoma cells, including IFN-γ and TNF-α secretion and release of cytolytic granules." (PMID 33946954, 2021). "In leukemia cells, MEL can increase tumor necrosis factor (TNF) toxicity by activation of PLA2." (PMID 33396195, 2020). "Furthermore, in B-CLL patients, TNF-α serum concentrations and soluble TNF-α receptor (sTNFR) concentrations are augmented, and correspondence with leukemia progression has been revealed." (PMID 32102441, 2020). "Overall, both forms of TNF-α contribute to leukemia progression, but much work has to be done to deepen our understanding of the different mechanisms in which they are involved and to develop new specific anti-TNF-α therapies against leukemia." (PMID 32443460, 2020). "An early study showed that ERK5 does not affect cell cycle progression of leukemia T cells, but it makes Jurkat T cells more sensitive to tumor necrosis factor α (TNFα)." (PMID 30901834, 2019). "Moreover, TNF stimulation stimulates the JNK pathway, leading to the up-regulated expression of anti-apoptotic genes in leukemia cells." (PMID 31546831, 2019). "However, incubation of THP-1 leukemia cells with stimulated M-CM induced a significant cytokine expression in THP-1 cells (8-fold increase of IL-6, 18-fold induction of TNFα and nearly 13-fold in MCP-1 expression)." (PMID 28832545, 2017). "It is reported that TNF-alpha, SIN3A and SIN3-HDAC complex have close relationship with leukemia." (PMID 26822725, 2016). "As TNF-α itself is known to lead to cancer cell death, we tested whether the levels of TNF-α produced could lead to direct leukaemia cell death." (PMID 27040177, 2016). "Quantitative measurement of the serum cytokines in mice after the induction of leukemia (WEHI-3) revealed the IL-10 level at 156.30±4.10 pg/mL, whereas the levels of IFN-γ, TNF-α, IL-12β, and IL-2 were 52.63±5.03, 42.63±3.77, 185.40±15.24, and 14.81±0.74 pg/mL, respectively." (PMID 26752299, 2016).
leukemia (continued). "Furthermore, we proposed to evaluate the patterns of dendritic cell lineages and of a subset of immunomodulatory cytokines (IL-10, TNF-α, IL-6, and IL-1β) during the course of ITD+ leukemia." (PMID 23616009, 2013). "Specifically, TNF-α mediates increased CXCL1 expression in CML BMSCs through signal transduction pathways, interacting with highly expressed CXCR2 in LSCs, thereby inducing a CXCR2 selection-dependent mechanism leading to the unlimited expansion of LSCs and leukemia progenitor cells." (PMID 40427609, 2025). "Data on anti-leukaemia activity were also corroborated by the quantification of inflammatory cytokines, namely granzyme B (Granz B), interferon gamma (IFN-γ) and tumour necrosis factor alpha (TNF-α), both in vitro and in the plasma of mice treated with CAR.CD123-NK cells." (PMID 36335396, 2022). "Therefore, transferring IL-27 pre-stimulated polyclonal iTregs reduces systemic TNFα secretion, the expansion of cytokine secreting donor CD4 and CD8 T cells, and inflammatory cell infiltration in the colon, while preserving the graft-versus-leukemia activity." (PMID 32117306, 2020). "High frequencies of TNF-α+ IFN-γ+ cells and TNF-α- IFN-γ+ CD8+ T cells were observed before in vitro antigen stimulation, suggesting that the CTLs might respond to antigen expressed by leukemia cells in vivo." (PMID 26658107, 2015). "In that regard, we evaluated if cytokines (IL-10, TNF-α, IL-6, and IL-1β) proposed by several groups as indicators of a broad range of immunopathological conditions affecting cancer could also serve as potential biomarkers to predict ITD+ leukemia relapse." (PMID 23616009, 2013). "The inflammatory cytokines IFN-γ and TNF-α change the BMSC secretome and we hypothesized that factors produced by tumors or leukemia would also affect the BMSC secretome and investigated the interaction of leukemia cells with BMSCs." (PMID 24304929, 2013). "It is known that progenitor cells (CD34+) in the bone marrow may express Fas in response to tumor necrosis factor-alpha (TNF-α) and interferon-gamma (INF-γ) in vitro and cytotoxic T lymphocytes in T-LGL leukemia may spontaneously produce INF-γ and TNF-α after stimulation." (PMID 18474096, 2008). "We investigated the influence of recombinant human tumour necrosisfactor alpha (TNF-α) and its derivatives termed muteins III, V,VI—in which the first 3 to 7 amino acids of native TNF-α have beenreplaced—on the survival time of mice inoculated with leukaemiaL1210 or leukaemia P338." (PMID 18475588, 1994). "Zhang’s research revealed that a single TIGIT inhibitor upregulated only IFN-γ and TNF-α, but the combination of anti-TIGIT and anti-PD-1 inhibitors significantly upregulated IL-2, IFN-γ, and TNF-α in CD4+ or CD8+ T cells, which could enhance anti-leukemia immune response." (PMID 37291608, 2023). "The present study revealed that TGF-β, alone or combined with TNF-α, was able to decrease the expression level of Gli2 in the KG-1 cell line, thus suggesting that TGF-β may be one of the signaling molecules that plays a key role in the regulation of the Gli2 gene in leukemia cell lines." (PMID 25009639, 2014). "IFN-γ KO/KD also did not decrease the efficacy of anti-CD19 CAR Ts against leukemia/lymphoma models, while decreased the levels of some inflammatory cytokines (MCP-1, MIP-1β, IL-6, TNF-α, and IP-10) and macrophage activity markers (CD80 and CD86)." (PMID 41354926, 2025).
cognitive decline (277 papers, 2011 to 2026). "A negative correlation was observed between TNF-α concentration and MMSE score (r = −0.400, p = 0.000), suggesting that higher TNF-α levels are associated with cognitive decline." (PMID 40137151, 2025). "TNF-α is known to be closely associated with a range of autoimmune and neurological disorders, including cognitive decline." (PMID 40109717, 2025). "This discussion supports the notion that targeting inflammatory mediators like IL-6 and TNF-alpha can be a viable strategy for managing neurodegenerative conditions associated with cognitive decline." (PMID 39906616, 2025). "Biochemical findings centered on inflammatory cytokines, particularly IL-6 and TNF-α, which were variably associated with cognitive decline depending on timing and assessment type." (PMID 41228315, 2025). "It has been shown that excessive activation of TNF-α triggering pathways results in cell death, damage to the blood–brain barrier, neuronal loss, cognitive decline, and long-term neurological complications." (PMID 40855885, 2025). "Higher levels of TNF-α have been associated with accelerated cognitive decline and mediate induction of depressive-like symptoms in humans and animal models." (PMID 39526037, 2024). "The presence of systemic inflammation with increased TNF‐α production is associated with increased glial cell activation, cognitive decline and neuroinflammation." (PMID 38332529, 2024). "Inflammatory markers, including CRP, interleukins, and tumor necrosis factor, were associated with neuroinflammatory processes, which can exacerbate synaptic dysfunction, promote neuronal injury, and contribute to cognitive decline." (PMID 39592894, 2024). "Among these cytokines, TNF-α is one of the most well-characterized cytokines in the pathogenesis of AD, as TNF-α levels are strongly associated with cognitive decline, neuronal toxicity, and cerebral apoptosis." (PMID 38459540, 2024). "Acute and chronic systemic inflammation associated with increased levels of tumor necrosis factor (TNF)-α, a typical inflammation-inducing cytokine, are associated with increased cognitive decline in AD." (PMID 37836458, 2023). "TNF-α is a proinflammatory cytokine that has been associated with more rapid cognitive decline in patients with AD." (PMID 37251808, 2023). "Aging-associated inflammatory cytokines, such as IL-6 and TNFα, were found to disrupt circuits that are involved in cognitive decline or dementia." (PMID 36615907, 2023). "TNF-α plays a role in immune-brain communication and increases the rate of cognitive decline, and is associated with reduced hippocampal volume." (PMID 37814231, 2023). "Elevated cerebrospinal fluid and plasma levels of Tumor Necrosis Factor-alpha (TNFa) and Interleukin-6 (IL-6) in AD patients predict further cognitive decline and have been linked to worse cognitive performance in both MCI and AD patients." (PMID 36900708, 2023). "In the analysis including CI-NAD, immune and endothelial markers were mainly associated with cognitive decline (|rho|> 0.36, p < 0.025), only TNFα was associated with neurodegeneration (rho = 0.37 with NfL, p = 0.028) and none with amyloid and tau pathology." (PMID 37254223, 2023). "Several studies also demonstrated that elevated blood TNF-α in AD patients is strongly associated with the rate of cognitive decline." (PMID 35328830, 2022). "After a two-year follow-up, AD patients with the highest BB-DNA tertile had a worse cognitive decline, while higher BB-DNA levels were associated with higher TNF-α and lower IL-10 in MCI." (PMID 36613538, 2022). "In humans, an increase in peripheral TNFα has been reported with age and is strongly associated with gray matter loss and cognitive decline." (PMID 34515928, 2021). "Inhibitors of TNF-α have exhibited potential promise to slow down the progress of AD-associated cognitive decline." (PMID 34685770, 2021). "A clinical study showed that the serum levels of TNF-α were associated with cognitive decline in AD patients." (PMID 33716675, 2021).